IL6 (interleukin 6)
Diseases named in the same sentence as IL6 in open-access papers (continued):
Sharing a sentence is not in itself a finding about the gene and the disease.
Stroke (continued). "Only the initial IL-6 and NO2 levels retained significance for functional outcome of stroke at one month, and cardiogenic strokes showed borderline significance (P = 0.057)." (PMID 21450100, 2011). "A positive correlation was established between the initial IL-6 CSF levels and the NIHSS scores on the seventh day of stroke (r = +0.52; P < 0.05)." (PMID 21450100, 2011). "The most prominent ones after stroke are interleukin-1β (IL-1β), tumor necrosis factor-α (TNF-α) and IL-6." (PMID 21040547, 2010). "Neurons highly express cytokines such as IL-6, -1β, and TNF-α in neurodegenerative diseases, including AD, spinal cord injury, stroke, and sciatic nerve injury." (PMID 21034511, 2010). "Only aliskiren was able to significantly reduce stroke-induced gene expression of CXC chemokine ligand 1, interleukin-6 and tumor necrosis factor-alpha in the ischemic core." (PMID 21124781, 2010). "Ex vivo, T cells of stroke patients proliferated unimpaired and released increased amounts of the proinflammatory cytokine TNF-α (p<0.01) and IL-6 (p<0.05)." (PMID 20090932, 2010). "Simulations of the post-stroke cytokine network over a 72-hour period yielded temporally distinct trajectories for tumor necrosis factor-alpha (TNF-α), interleukin-6 (IL-6), and interleukin-10 (IL-10), reflecting the transition from pro-inflammatory activation to immune resolution." (PMID 41557608, 2026). "The results revealed that PSD patients had significantly higher peripheral IL-6 levels in the acute phase of stroke than non-PSD patients did (SMD = 0.66, 95% CI = 0.42-0.90)." (PMID 41664439, 2026). "This study presents a mechanistically grounded computational model that captures the nonlinear interplay between TNF-α, IL-6, and IL-10 during acute post-stroke inflammation." (PMID 41557608, 2026). "Furthermore, while interleukin-1 (IL-1) is a critical mediator in post-stroke inflammation, our model focuses on the TNF-α/IL-6/IL-10 axis to establish a foundational understanding of their core feedback loops." (PMID 41557608, 2026). "Similarly, the relationship between inflammation, specifically through cytokines such as IL-6 and TNF-alpha, and stroke severity has been extensively studied." (PMID 39859987, 2025). "The identification of IL-6 and TNF-alpha as key contributors to post-stroke outcomes suggests that therapeutic strategies targeting cytokine modulation could be pivotal in improving rehabilitation trajectories and reducing long-term disability." (PMID 39859987, 2025). "Stroke can trigger the production of inflammatory markers such as C-reactive protein (CRP), interleukin-6 (IL-6), and tumor necrosis factor-alpha (TNF-α), which stimulate osteoclastogenesis and inhibit osteoblast function, leading to accelerated bone resorption and osteoporosis." (PMID 39792154, 2025). "Similarly, in the brain, activated microglia and astrocytes in stroke or neurodegeneration release IL-1β, TNF-α, IL-6, and matrix metalloproteinases that disrupt the blood–brain barrier and kill neurons and damage neural connections." (PMID 41462689, 2025). "Astrocyte-derived IL-6 further contributes to angiogenesis, neurogenesis, and neuronal differentiation by promoting the polarization of TH1 lymphocytes into TH2, facilitating recovery after stroke." (PMID 40305179, 2025). "Additionally, we aimed to examine the correlation between serum IL-6 levels, the severity of neurological deficits, and patient prognosis after AIS, depending on stroke volume." (PMID 40305179, 2025). "The positive correlation between IL-6, TNF-alpha, and NIHSS scores in our study suggests that these biomarkers are not only indicators of stroke severity but may also be utilized in the early prediction of functional outcomes." (PMID 39859987, 2025). "Some studies demonstrated that the addition of several biomarkers, such as NT-proBNP, hs-troponin T, d-dimer, IL-6 and troponin I, could improve the accuracy of the CHA2DS2-VASc score for predicting stroke and mortality in AF patients." (PMID 40073613, 2025).
Stroke (continued). "Emerging treatments targeting IL-6 and TNF-alpha present promising advances in post-stroke care." (PMID 39859987, 2025). "Other positive effects of anthocyanin preconditioning in inducing stroke have also been mentioned, such as improving spontaneous activity and memory, and reducing the levels of molecules involved in the inflammatory response such as TNF-a, IL-1B, and IL-6." (PMID 40724240, 2025). "Immunological and inflammatory biomarkers, including IL-1β, IL-6, TNF-α, IL-10, IL-8, IL-17, and CRP, have become indispensable tools in stroke research, offering insight into how the immune system shapes both the extent of brain injury and the trajectory of recovery." (PMID 40869247, 2025). "For example, in stroke models, increased lipid droplet accumulation in microglia influences pro-inflammatory phenotypic changes, leading to elevated secretion of factors like TNF-α, IL-6, and IL-1, which exacerbate neuroinflammation." (PMID 40182755, 2025). "Additionally, TMAO levels are positively correlated with the expression of various pro-inflammatory cytokines, such as IL-6 and TNF-α, which play a crucial role in post-stroke neuroinflammation." (PMID 40625834, 2025). "Higher levels of IL-6 and IL-18 are related to PSD at 2 weeks and 1 year after stroke." (PMID 40529498, 2025). "IL-6 is a key marker of inflammation, and its concentration rises dynamically in serum within a few hours of AIS and can remain elevated for up to 3 months after the stroke." (PMID 40305179, 2025). "Similarly, pro-inflammatory cytokines IL-1β, IL-6 and TNF-α were significantly upregulated in the Stroke group relative to Sham controls (p < 0.001)." (PMID 41388741, 2025). "IL-6 demonstrates limited utility as a prognostic biomarker due to its lack of specificity in distinguishing stroke from other inflammatory or systemic disorders." (PMID 41227149, 2025). "In addition, pathway analysis of our RNA-seq data revealed that TNFα signaling, IL6/STAT3 signaling, and epithelial–mesenchymal transition (EMT) gene signatures were increased in PPARα KO stroke brains." (PMID 40362325, 2025). "Recent studies have also highlighted the dynamic interplay between IL-6 and TNF-alpha, suggesting that the balance between these cytokines may significantly affect the inflammatory environment in the post-stroke brain." (PMID 39859987, 2025). "Additionally, sex differences in inflammatory markers such as IL-6, CRP, and S100B were observed, with these biomarkers being more elevated in female stroke patients." (PMID 40356948, 2025). "Furthermore, the exacerbating role of inflammatory cytokines such as IL-6 and TNF-α in stroke outcomes is well-established." (PMID 40313968, 2025). "IL-6, along with other inflammatory cytokines such as TNF-α and IL-1β, may play an important role in cognitive impairments following a stroke, as they are key regulators of the acute phase response to inflammation and tissue damage." (PMID 40305179, 2025). "The absence of multi-year IL-6 surveillance prevents a robust evaluation of its long-term predictive value in restenosis, recurrent stroke, and cardiovascular mortality events." (PMID 41440557, 2025). "In addition, it was also able to significantly inhibit PAF, IL-6, TNF-α, ICAM-1, and VCAM-1, which significantly improved cognitive function, attenuated anxiety-like behaviors, and promoted post-stroke brain function and motor recovery in stroke rats." (PMID 40837062, 2025). "IL-6, NSE, S100B, and miR-124 usually increase within 3–12 h of a stroke." (PMID 40949500, 2025). "However, in vitro analyses of human blood samples of healthy controls and stroke patients incubated with CLA showed a significantly decreased production of IFN-γ and TNF-α, and a visual decrease of IL-17A and IL-6." (PMID 39372701, 2024).
Stroke (continued). "When stroke occurs, the NF-κB inflammatory signaling pathway is activated to stimulate the phosphorylation of P65 protein to p-P65, and then p-P65 enters the nucleus to further induce the release of inflammatory factors including TNF-α, IL-1β and IL-6 etc.." (PMID 38756375, 2024). "In our experiment, the post-surgical assessment of proinflammatory cytokines, including IL-1β, IL-6, and TNF-α in the hippocampal tissue, revealed that the inflammatory response in the CNS of mice with stroke was markedly higher than that in mice undergoing sham operations." (PMID 39758888, 2024). "After stroke onset, activation of microglial AHR by microbial Trp-derived ligands was corroborated to suppress the expression of proinflammatory and neurotoxic genes, including TNF, IL6, IL12A, and NOS2, and boost anti-inflammatory IL10 expression." (PMID 39195495, 2024). "Serum levels of TMEM166 (12.54 ± 3.74 ug/mL vs 38.01 ± 10.01 ug/mL, p<0.01), IL-6 (1.02 ± 0.27 pg/mL vs 3.08 ± 0.78 pg/mL, p<0.05) and CRP (1.64 ± 0.6 ng/mL vs 3.09 ± 1.38 ng/mL, p<0.05) after CEA in perioperative stroke patients were statistically higher than in patients within the control group." (PMID 37611898, 2024). "In addition to the anti-inflammatory roles of IL-10 in the inflammatory response after stroke, IL-10 is also a negative regulator of pro-inflammatory cytokines TNF-α, IL-1β and IL-6." (PMID 38421829, 2024). "Variations in genes such as IL-6 and TNF-α may affect inflammatory responses and stroke development." (PMID 39655053, 2024). "An increasing body of research has reported a correlation between cognitive impairment following stroke and alterations in the production of biomarkers, including C-reactive protein (CRP), interleukin 6 (IL-6) and interleukin 10 (IL-10), which are found in blood, urine and other body fluids." (PMID 38984252, 2024). "Therefore, investigation the prognostic value of markers in the NETs/AIM2 inflammasome axis, such as MPO-DNA, PAD4, HMGB1, C1q, AIM2, ASC, Caspase-1, IL-1β, IL-6 and IL-8, in LAA stroke patients is a meaningful endeavor." (PMID 39737165, 2024). "Stroke-induced alterations in microglia and astrocytes emerge as critical in PSD evolution, modulating neurotransmitter dynamics, neuronal viability, and cytokine release, including pro-inflammatory IL-1β, IL-6, TNF-α, and anti-inflammatory IL-10." (PMID 38377025, 2024). "Investigations into cytokine levels in stroke models with exercise intervention consistently report reductions in pro-inflammatory cytokines, such as tumor necrosis factor alpha (TNF-α), IL-1β, and interleukin 6 (IL-6)." (PMID 38911597, 2024). "Patients who received an intermediate dose of canakinumab had a reduced occurrence of the primary endpoint, a composite of cardiovascular death, nonfatal acute myocardial infarction, or nonfatal stroke, accompanied by a reduction in IL-6 and CRP." (PMID 38274622, 2024). "In both types of stroke, there is a robust inflammatory reaction characterized by neutrophil and macrophage activation, along with the release of inflammatory mediators like tumor necrosis factor-α (TNF-α), interleukin-6 (IL-6), and C-reactive protein (CRP)." (PMID 39329013, 2024). "Furthermore, hNSC transplantation reduces infarct size and proinflammatory factor (TNF-α, IL-6, and IL-1β), matrix metalloproteinase-9 (MMP-9), and MMP-3 expression in aged stroke mice." (PMID 37728582, 2024). "Additionally, the levels of serum IL-6 and CRP in stroke patients after CEA were 3.08 ± 0.78 pg/mL and 3.09 ± 1.38 ng/mL respectively, which were significantly higher than those in the control group (1.02 ± 0.27 pg/mL, 1.64 ± 0.6 ng/mL, respectively)." (PMID 37611898, 2024). "Interestingly, stroke mice with HFD showed a significant upregulation of plasma TNF-α, IL-6 and MCP-1 amounts compared to sham controls within 3 h after stroke onset." (PMID 39845972, 2024).
Stroke (continued). "We reanalyzed plasma IL-1β, IL-6, TNF-α, sICAM-1, sVCAM-1, and FKN levels data obtained in a previous study to test potential differences between HGS stroke patients (within 7 days or 1-year from stroke onset) and healthy controls." (PMID 36536168, 2024). "Both IL6 and CCL2 lose rhythmicity in response to clock disruption resulting in the generation of pro-inflammatory macrophages, which increase the severity of stroke 45,47,48." (PMID 38169640, 2024). "Similarly, significant evaluation of IL-6,TNF-α, and IFN-γ levels has been found in PSD patients one year after stroke." (PMID 38421829, 2024). "Additionally, direct comparisons between CIRP and established biomarkers, such as C-reactive protein, IL-6, and TNF-α, should be conducted to assess their predictive value, sensitivity, and specificity for stroke outcomes." (PMID 37521290, 2023). "SARS-CoV-2 stroke patients have experienced elevated levels of biomarkers that rise in inflammation such as hs-CRP, IL-6, and D-dimer, comparing to noninfected stroke patients." (PMID 37260778, 2023). "Of the blood markers identified here as being relevant for the long-term outcome after stroke, arguably the most important molecular key players are tumor necrosis factor alpha (TNF), interleukin 6 (IL6), fibrinogen (FGA), and plasminogen activator inhibitor-1 (SERPINE1)." (PMID 35953740, 2023). "According to the results, a high dose of vitamin D can improve the National Institute of Health Stroke Scale and decrease interleukin-1 and interleukin-6 levels, although these changes were not statistically significant." (PMID 38024000, 2023). "Within 24 h of symptom onset, the expression of miRNA‐9, ‐124 and ‐134 was positively correlated to poor prognosis of stroke patients assessed through the National Institutes of Health Stroke Scale (NIHSS), infarct volume and serum levels of interleukin‐6 (IL‐6)." (PMID 35421904, 2023). "Similarly, herein, we revealed that the IL‐1β, TNF‐α, IL‐6 and IFN‐γ mRNA contents enhanced after the development of ischemia in tMCAO stroke rats, whereas, these expressions were diminished after engeletin treatment." (PMID 37132060, 2023). "In a rat stroke study on MnTnHex-2-PyP5+, we have demonstrated the inhibition of NF-κB and subsequent downregulation of NF-κB-controlled pro-inflammatory cytokines, TNF-α and IL-6." (PMID 37891940, 2023). "Therefore, the aim of this study is to assess the predictive value of combining iFABP, IL-6, and TNF-α testing for the onset of PSD in hospitalized stroke patients." (PMID 38084247, 2023). "The estimate of IL-6 did not remain statistically significant when modelled with stroke and was not retained." (PMID 38455939, 2023). "I/R caused an increase in pro-inflammatory cytokines (IL-1beta, IL-6, TNF-alpha) at 6-h or 24-h of I/R, but not in the subacute (72-h) phases of stroke." (PMID 37822799, 2023). "In addition, we also found such a relationship with IL-6 assessed in less than 4.5 h and on the seventh day, and CCL5 in less than 4.5 h (R = 0.16; 0.22) since the stroke." (PMID 37759440, 2023). "In this study, we report for the first time that stroke in T2DM mice induces earlier and higher inflammatory factor, cytokine, and acute phase response protein expression such as SAA, NLRP3, IL-1β, IL-6, TNFα, and TLR4 in the liver compared to heart and kidney." (PMID 36968490, 2023). "Interestingly, cromolyn treatment led to a significant downregulation of both IL-6 and CXCL1 levels in the blood plasma post-stroke." (PMID 37805585, 2023). "A case-control study of 680 patients with minor stroke or TIA, with systematic exclusion of patients with confounding infection or pro-inflammatory diseases, found that higher baseline levels of IL-6, IL-8 and high sensitivity (hs) CRP independently predicted one-year recurrent vascular events." (PMID 41541100, 2023).
Stroke (continued). "In animals of both sexes, post-stroke WBV significantly reduced circulating pro-inflammatory cytokines IL-6, IFN-gamma, and TNF alpha as compared to the respective No-WBV group." (PMID 36062148, 2022). "When separated by history of previous stroke, systemic and vascular inflammation (assessed by IL-6 and VWF respectively) no longer significantly contributed to the risk of death." (PMID 35042473, 2022). "Similarly, high systemic levels of such pro‐inflammatory cytokines (IL‐6, TNF‐α and IL‐1β) have been directly related to cytokine‐induced sickness behavior after experimental stroke." (PMID 35971650, 2022). "IL6 levels were significantly higher (p < 0.0001) for patients with negative NI arriving at the hospital 360 min after the stroke onset." (PMID 34165728, 2022). "Administration of LCN-2 mAb prior to full post-stroke LCN-2 elevation reduced the levels of LCN-2 and pro-inflammatory mediators (iNOS, IL-6, CCL2, and CCL9) and resulted in neutrophil infiltration, BBB leakage, cerebral infarction induction, and improved functional outcomes after stroke." (PMID 35493318, 2022). "The one‐way ANOVA analysis revealed that IL‐1β and IL‐6 transcripts were upregulated in response to stroke (p < 0.001), while mRNA expression of IL‐10 did not change relative to sham (p = 0.20)." (PMID 35715988, 2022). "Moreover, Il10-KO CD8+ TRL–treated mice exhibited increased brain expression of IL-6, CCL1, and CCL2 after stroke compared with WT CD8+ TRL–treated mice." (PMID 35912857, 2022). "The key finding from this study is that whilst CRP retained significant independent association with mortality in the subgroup of patients with previous stroke, IL-6 and VWF did not." (PMID 35042473, 2022). "We have shown that serum IL-6 concentration above 4 pg/mL and TNF-α > 37 pg/mL, determined on the 7th day after stroke, may indicate a high probability of death in patients." (PMID 36142524, 2022). "In addition to a TH2 shift, there are also increases in inflammatory factors, including IL-6 and CRP, following stroke." (PMID 38566903, 2022). "The pro-inflammatory (TNF-α, IL-1β, IL-6, IL-12 p40, and MIP-1α), and the anti-inflammatory (IL-4 and IL-10) mediators were examined by ELISA in IRF5 or IRF4 CKO aged mice plasma, 3 days after stroke." (PMID 35963621, 2022). "Stroke-induced cytokines (IL-6, TNF-α, and IL-1β) and MCP-1 and CCR2 mRNA levels were significantly higher in the diabetic brain compared to control at 1 day after MCAO, and this increased expression was sustained until 3 days post-stroke." (PMID 35784349, 2022). "Although they are not stroke-specific markers, such as interleukin 1 (Il-1), interleukin 6 (Il-6) or tumour necrosis factor-α (TNF-α), they suggest the existence of immunological activation in the course of the inflammatory process and tissue damage." (PMID 35330458, 2022). "Fourth, we only measured the baseline level of IL-6 and did not analyze the clinical outcomes of stroke with respect to the dynamic changes in IL-6 at different time points." (PMID 33927687, 2021). "On the other hand, MEDS-23 did not significantly reduce post-stroke mortality nor did it prominently influence the levels of brain IL-6 and TNF-α in post-stroke rats." (PMID 35053779, 2021). "CBA-analyses of plasma samples, taken at 24 h post-stroke, using the mouse inflammation kit of the BD CBA, revealed significantly lower IL-6 levels in mice treated with ADA-409-052 (5.38 ± 0.354 pg/ml) when compared with vehicle-treated mice (8.27 ± 1.06 pg/ml, p = 0.027)." (PMID 33568697, 2021). "Among all the patients with recurrent stroke, 178 (12.66%), 109 (10.67%), 434 (11.0%), and 338 (7.69%) had PolyVD with IL-6 ≥ 2.64 pg/mL, PolyVD with IL-6 < 2.64 pg/ml, non-PolyVD with IL-6 ≥ 2.64 pg/ml, and non-PolyVD with IL-6 < 2.64 pg/ml, respectively." (PMID 33927687, 2021).